MDM2 (MDM2 proto-oncogene)
Diseases named in the same sentence as MDM2 in open-access papers (continued):
Sharing a sentence is not in itself a finding about the gene and the disease.
melanoma (158 papers, 2008 to 2025). A malignant, usually aggressive tumor composed of atypical, neoplastic melanocytes. "MDM2 inhibitors not only promote IL-15 production by cancer-associated fibroblasts, macrophages, and B cells but also increase IL-15 production by melanoma cells, with high IL-15 expression positively correlated with mouse viability." (PMID 39263534, 2024). "Our findings in this large population-based melanoma study now pave the way for further replication studies and for research to unveil the potential underlying mechanisms involving Mdm2/Mdm4 with melanoma development and outcomes." (PMID 37345045, 2023). "Our results suggest that MDM4/MDM2 variants are associated with the development of subsequent primaries and with the death of melanoma in a sex-dependent manner." (PMID 37345045, 2023). "Specifically, females, but not men, with the MDM4 rs4245739*C allele were more likely to develop multiple primaries, and those with the MDM2 SNP309*G allele were less likely to succumb to melanoma compared with those carrying the C allele." (PMID 37345045, 2023). "Formal analyses demonstrated that females, but not males, who carried the variant MDM4-rs4245739*C were more likely to develop a new primary melanoma, and those with the variant MDM2-rs2279744*G were less likely to succumb to the disease." (PMID 37345045, 2023). "Our data provide some evidence for sex-specific associations of MDM4-rs4245739 and MDM2-rs2279744 (SNP309) with melanoma risk and survival, respectively." (PMID 37345045, 2023). "In recent work, the combination of CDK4 and MDM2 inhibitors demonstrated significant preclinical activity, and this combination was effective in melanoma models with genetic loss of CDKN2A." (PMID 33076392, 2020). "Furthermore, with an immunohistochemical evaluation of primary melanomas and lung tumors, which exhibit highly activated p90RSK compared to corresponding normal tissue, we demonstrated that MDM2 stabilization was associated with p90RSK phosphorylation." (PMID 39329730, 2024).
melanoma (continued). "Mdm2 overexpression could be linked to gene amplification in several malignancies (eg, malignant melanoma, non-small cell lung cancer and lipomatous tumours but in PCa a specific Mdm2 gene amplification could not be demonstrated by Southern blot analysis so far." (PMID 18577987, 2008). "In this study, we report that MMRi62 has advantages over conventional MDM2 inhibitors in cell death induction in melanoma cells and SC-62-1 as MMRi62 derivatives has improved activity and is useful in eliminating melanoma cells with acquired resistance." (PMID 40649216, 2025). "Two studies revealed that melanomas resistant to CDK4/6i treatment exhibited higher levels of MDM2 and MDM4 proteins compared to treatment-sensitive cells." (PMID 40282469, 2025). "We have previously demonstrated that combined treatment with a CDK4/6 inhibitor and an MDM2 inhibitor suppresses the growth of melanoma patient-derived xenografts and that knockdown of CDK2 overcomes resistance to CDK4/6 inhibition." (PMID 40904502, 2025). "On the other hand, a study conducted by Vanderbilt University Medical Center explored how MDM2 influences resistance to CDK4/6 inhibitors in melanoma treatment." (PMID 39200315, 2024). "To this end, we performed immunohistostaining for pRSK and MDM2 in 12 primary lung tumors, 12 melanomas and five prostate tumors, comparing each to its normal counterpart." (PMID 39329730, 2024). "Nonetheless, these results and considerations open new perspectives for expanding the use of MDM2 inhibitors in both p53wild-type and p53mutated melanoma." (PMID 39451196, 2024). "In another study, MDM2 inhibitors combined with anti-PD-1 antibodies in melanoma-bearing mice resulted in improved survival and fewer lung metastases compared with the treatment of MDM2 inhibitors alone." (PMID 39263534, 2024). "With the computational pipeline used in this study, we were successful in the identification of key protein signatures (AKT1 and MDM2) in melanoma from a core regulatory network that is based on a published E2F1 interaction map." (PMID 37993971, 2023).
melanoma (continued). "The study of NNMT, PON2, Nrf2, MITF, IDO, and MDM2 as potential biomarkers in melanoma holds great promise for improving diagnosis and advancing targeted therapies." (PMID 37629523, 2023). "No other statistically significant associations were observed between the tested MDM2 and MDM4 variants and multiple melanoma or death in melanoma patients." (PMID 37345045, 2023). "Using logic-based in silico perturbation experiments of a core regulatory network, we identified that simultaneous perturbation of Protein kinase B (AKT1) and oncoprotein murine double minute 2 (MDM2) drastically reduces EMT in melanoma." (PMID 37993971, 2023). "This retrospective cohort study investigated the association between tumor SURVIVIN and MDM2 expression levels and treatment response or clinical outcomes in patients undergoing ILP for in-transit melanoma metastases." (PMID 38138884, 2023). "To identify credible SNPs responsible for, or contributing to, the effect of the tested MDM2/MDM4 SNPs on melanoma, we mined public databases." (PMID 37345045, 2023). "Our model simulations identified two protein signatures AKT1 and MDM2 as potential drivers of EMT in melanoma." (PMID 37993971, 2023). "Borderline significance was identified for the interaction between MDM4 rs4245739 * MDM2 rs117039649 on melanoma-specific survival (Pinteraction 0.14)." (PMID 37345045, 2023). "We investigated the expression profiles of AKT1 and MDM2 and their impact on melanoma patient survival using the Kaplan-Meier curve using the TCGA melanoma SKCM dataset." (PMID 37993971, 2023). "The knockdown of USP15 results in the decrease in the E3 ubiquitin ligase MDM2 protein in the melanoma cell line A375 and the colorectal cancer cell line HCT116, indicating that USP15 plays an important role in stabilizing MDM2." (PMID 35203682, 2022). "This comparison, although not performed in the same experiment, indicate that Navtemadlin is a potent MDM2 inhibitor in murine melanoma cells as well." (PMID 36922937, 2022). "Since MDM2 is an important target in melanoma, the monoclonal antibody 3G5 is chosen for intracellular transport." (PMID 35401191, 2022). "Co-administration of MDM2 inhibitor was beneficial in melanoma cells resistant to CDK4/6 inhibition, characterised by abnormal PI3K/AKT (phosphoinositide 3-kinase/protein kinase B) signalling, and CDK4/6 inhibition upregulated cyclin D1 that sequestered p21." (PMID 34911439, 2021). "The drug response pattern observed across tumour types matched well with our MI-773 and Nutlin-3a internal data: leukaemia, lymphoma, melanoma, neuroblastoma, mesothelioma, and renal cancer were the most sensitive tumour types to MDM2 inhibition." (PMID 34711913, 2021). "Other oncogenes that are epigenetically regulated and important for melanoma tumorigenesis include MDM2 and BCL-2." (PMID 34944799, 2021).
melanoma (continued). "On the other hand, triple wild-type melanoma was found to exhibit MDM2/4 amplifications in about 15% of the cases." (PMID 32110946, 2020). "Previous studies showed that targeting MDM2 or MDMX resulted in a therapeutic effect on killing melanoma cells and tumorigenicity." (PMID 32686661, 2020). "We have recently reported a case of an acral melanoma patient with extensive MDM2 amplification, suffering hyperprogression under combined checkpoint inhibition with ipilimumab and nivolumab." (PMID 32110946, 2020). "MDM4 overexpression renders most primary melanoma cultures relatively immune to specific MDM2 inhibition." (PMID 31374895, 2019). "Amplification or overexpression of Mdm2 and MdmX occur in a wide range of tumors, including malignant melanoma." (PMID 31181622, 2019). "In a word, via increasing hnRNPA1 level and then reducing the expression of MDM2, estradiol prevented carcinogenesis in melanomas." (PMID 28035066, 2017). "Although MDM2 overexpression due to gene amplification is rare, post-transcriptional mechanisms determine the frequent upregulation of MDM2 expression in melanoma cells." (PMID 29156643, 2017). "The mouse double minute-2 gene (MDM2) is an oncogenic gene that is overexpressed in various types of cancers including melanoma." (PMID 28035066, 2017). "In summary, the estradiol is a rationally anti-skin cancer agent that induces MDM2 down-regulation via enhanced hnRNPA1 expression, and controls the oncogenic activities of MDM2 in melanomas in vitro/vivo testing." (PMID 28035066, 2017).
melanoma (continued). "Our data demonstrated that estradiol prevented proliferation, migration and EMT progression of melanomas in vitro by increasing the expression of hnRNPA1 and then influencing the level of MDM2 in melanomas." (PMID 28035066, 2017). "Another mechanism stimulating MDM2 expression in melanoma cells is related to AXL receptor signaling." (PMID 29156643, 2017). "Results indicated that silence of hnRNPA1 led to the increase of MDM2 at protein levels, which can be observed obviously in melanoma cells (P<0.05)." (PMID 28035066, 2017). "A clinical trial of MEK and MDM2 inhibition in melanoma is planned at Vanderbilt University Medical Center." (PMID 25537510, 2015). "Recently, it has been reported that in a fraction of melanoma tumors MDM2 expression is upregulated owing to the silencing of a microRNA, miR-18b, that targets Mdm2 mRNA." (PMID 24743024, 2014). "Recently, MDM4 over MDM2 has been shown to be overexpressed in cells freshly isolated from primary and metastatic melanomas compared to cultured melanoma cell lines, the later being likely selected for MDM2 overexpression." (PMID 24416617, 2013). "In the first group, MDM2 was the only cancer gene amplified and over-expressed in more than one melanoma sample." (PMID 21494657, 2011). "Interestingly, MDM4 is overexpressed in ~65% of cutaneous melanomas, whereas MDM2 has lower levels of upregulation in melanomas." (PMID 39273363, 2024). "Finally, we have highlighted the existence of a significant correlation between p90RSK activation and MDM2 stabilization in primary lung tumors and melanomas." (PMID 39329730, 2024). "Furthermore, the MDM2 inhibitor ALRN-6924 induced a viral mimicry response and tumor inflammation signature genes in melanoma patients, which provided a rationale for the synergistic strategy of MDM2 inhibitors and immunotherapy." (PMID 36600243, 2023). "Thus, it is plausible that these credible variants in MDM2 and MDM4 modify the risk for melanoma and survival in melanoma patients." (PMID 37345045, 2023). "Preclinical evidence suggests that the drug combination with MEK and MDM2 (mouse double minute 2) inhibitors may also act synergistically in the treatment of melanoma." (PMID 36361773, 2022).